GJA1 (gap junction protein alpha 1)
Diseases named in the same sentence as GJA1 in open-access papers (continued):
Sharing a sentence is not in itself a finding about the gene and the disease.
cancer (311 papers, 2005 to 2026). A tumor composed of atypical neoplastic, often pleomorphic cells that invade other tissues. "As these processes are associated with cancer progression, a potential link between Cx43 functions, mitochondrial activity and GJA1-20k expression can be postulated in this context." (PMID 39936974, 2025). "Materials and Methods: Several biological databases were used to evaluate the expression levels of GJA1 (encoding Cx43) and its diagnostic and prognostic significance in pan-cancer." (PMID 38792963, 2024). "The loss of Cx43-based gap junctions in cancer cells can be due to genetic or epigenetic changes of the gene encoding Cx43 (GJA1) or to dysregulation of Cx43 post-translationally." (PMID 38597989, 2024). "We also evaluated the hallmark of cancer related to the evasion of growth suppression by testing the gene expression of a specific gap junction gene called connexin 43 (Gja1), the most prevalent connexin in lung epithelial cells." (PMID 39771097, 2024). "In our study, we employed ROC curve analysis and Kaplan–Meier survival curve analysis to assess the diagnostic and prognostic significance of GJA1 in pan-cancer." (PMID 38792963, 2024). "Despite extensive investigations of Cx43(GJA1) expression and its corresponding activity in cancer evolution, few studies have focused on the effect of SNPs in GJA1 on cancer risk or prognosis." (PMID 34221012, 2021). "GJA1, which encodes Cx43, has been shown to synthesize several truncated protein forms through a process of internal translation initiation regulated by key cancer signalling pathways such as mTOR and Mnk1/2." (PMID 30845770, 2019). "In addition, mTOR, a factor implicated in GJA1-20k expression in cardiac and cancer cells, was also associated with the trafficking of mitochondria to the cortical cytoskeleton, thereby supporting lamellipodia dynamics in epithelial cancer cells." (PMID 39936974, 2025). "The high GJA1 expression in SCC cancer cells is associated with poor survival of patients." (PMID 35664298, 2022). "Alternative splicing was pervasive, with recurrent high-magnitude events at cancer-relevant loci including GJA1 (SE), NF2 (A3/A5), LIN37 (A5), ECT2 (A3/A5), BCL2L11 (A3), UQCRH (A5), CSE1L (A3), BROX (A3), and multiple ZNFs." (PMID 41952686, 2026). "Recently, six isoforms of Cx43 have been described and one of them, called GJA1-20k, has also been found to be expressed in cancer cells." (PMID 39936974, 2025). "Taken together, as initially demonstrated in the cardiac model, these findings unveil a chaperone effect of GJA1-20k that should be considered, given the promigratory role of membranous Cx43 observed during the progression of cancer." (PMID 39936974, 2025). "In the same study, chemical inhibition or genetic deletion of MAP kinase-interacting serin/threonine-protein kinase 1⁄2 (Mnk1/2), as well as inhibition of the EGFR pathway, also led to increased endogenous GJA1-20k expression in both primary and cancer cells." (PMID 39936974, 2025). "Along the same lines, given the role played by Cx43 CT in cancer cell abilities and the shared sequence with GJA1-20k, a putative role of the short isoform must be addressed." (PMID 39936974, 2025). "Given the ambiguous role of Cx43 in the cancer phenotype, the level of GJA1-20k, which modifies the proportion of membranous Cx43, must be considered for its impact on the intrinsic properties of cancer cells." (PMID 39936974, 2025). "The results revealed that GJA1 was accurate (AUC > 0.7) in predicting eight types of cancer, especially highly accurate (AUC > 0.9) in predicting CHOL." (PMID 38792963, 2024). "Previous studies have shown that GJA1 expresses excellent cancer-inhibitory effects in a variety of cancers, which is consistent with our findings." (PMID 38684858, 2024). "First of all, the evaluation of GJA1 expression across various cancers was based solely on data from the TCGA, The Protein Atlas, TISIDB, and STRING databases." (PMID 38792963, 2024).
cancer (continued). "Genes with known implications in cancer, such as MMP-13, KRT84, OLFM4, GJA1, AMOT and ADAMTS1, were strongly linked to DSG3 overexpression." (PMID 38067138, 2023). "GJA1 is a highly attractive target for delivering drugs directly into the cytoplasm of cancer cells, due to the permeability of gap junction channels to small molecules and macromolecules." (PMID 35664298, 2022). "The major truncated form, named GJA1-20k, corresponds to the C-terminal tail of Cx43 and can interact with numerous proteins and regulate malignant features in cancer cells, including proliferation, migration, and epithelial-to-mesenchymal transition (EMT)." (PMID 33003486, 2020). "The role of gap junction family in cancers has been widely studied, among which GJA1 is one of the most studied genes." (PMID 33299882, 2020). "In summary, for the drug target protein GJA1, that is known to be cancer-related, PathwayLinker predicts novel signaling pathway memberships." (PMID 22558382, 2012). "We can therefore postulate that findings from studies focusing on the role of Cx43 CT in cancer progression might also be relevant to GJA1-20k, particularly in cellular processes such as proliferation, apoptosis or migration." (PMID 39936974, 2025). "Among these evaluated cancer types, GJA1 predicted CHOL with high accuracy (AUC > 0.9)." (PMID 38792963, 2024). "The role of GJA1-20k in cancer pathology is also gaining attention." (PMID 39765713, 2024). "In addition, treatment inhibited GJA1, a gap junction protein that has been proposed to promote cancer development and metastasis." (PMID 34103518, 2021). "Many studies have also reported the role of GJA1 in promoting cancer progression." (PMID 33299882, 2020). "The role of GJA1 in cancers has been widely studied in recent years." (PMID 33299882, 2020). "Thirdly, GJA1 could also accelerate cancer progression by promoting cell migration via activating p38." (PMID 33299882, 2020). "For exogenous introduction, GJA1-11k is a small, hydrophilic, nucleus-targeted peptide that could be exploited for cancer therapy." (PMID 32244859, 2020). "Since GJA1 mutations are absent even in malignant tumors, posttranslational effects, which require clarification, can be reasoned behind this defective phosphorylation." (PMID 25933380, 2015). "In the third case study we analyze GJA1, an anti-cancer drug target protein in human, and predict for this protein novel signaling pathway memberships, which may be sources of side effects." (PMID 22558382, 2012). "Three anti-cancer drugs – cisplatin, mercaptopurine, and methotrexate – have known effects on GJA1." (PMID 22558382, 2012). "Furthermore, genes encoding proteins for cell adhesion, such as GJA1 and ITGB5, were downregulated, suggesting a loss of cell-to-cell communication, which may contribute to cancer progression." (PMID 40056285, 2025). "Therefore, it is plausible that high expression of GJA1 could potentially suppress the migratory ability of cancer cells in KIRC." (PMID 38792963, 2024). "We further assessed the effects of these PAHs on other hallmarks of cancer, namely, bronchoalveolar lavage fluid inflammatory infiltrates, pro-inflammatory transcripts, KC protein content, and mRNA expression of the gap junction (Gja1) and epiregulin (Ereg) genes." (PMID 39771097, 2024). "The molecular mechanismsof cancer pathway genes were deactivated,including COX, GJA1, CD44, FGF9, and CCND1." (PMID 38481680, 2024). "The expression of CDH6, DPYSLE3, GJA1, IL15, and ACTA2 is also relevant to survival in many types of cancers, but its mechanism of action in CRC requires further study to explore its impact." (PMID 34211976, 2021). "Moreover, many cancer-related pathways may be the critical pathways regulated by GJA1." (PMID 33299882, 2020).
cancer (continued). "Gap Junction Protein Alpha 1 (GJA1) belongs to the gap junction family and has been widely studied in cancers." (PMID 33299882, 2020). "Also, high-GJA1 mRNA expression levels could indicate a more unsatisfactory outcome in cancer." (PMID 33299882, 2020). "GJA1 (gap junction protein, alpha 1) involves in gap junction (GJIC), which plays important roles in cancer progression/metastasis." (PMID 25151146, 2014). "miR-7-5p/ABCC1/SLC7A5, miR-107/RAD51, miR-124-3p/ABCC4/SLC16A1/MGMT, miR-212-3p/ABCG2, miR-381-3p/GJA1 and miR-485-3p/SLC40A1 may modulate pathways that confer chemoresistance to cancer cells." (PMID 40061896, 2025). "This review synthetizes the current knowledge on GJA1-20k and its potential involvement in processes related to epithelial-to-mesenchymal transition (EMT) and the proliferation, dissemination and quiescence of cancer cells." (PMID 39936974, 2025). "For example, the “Cancer, Cellular Movement, Cellular Growth and Proliferation” network encompasses EGFR, FGFR2 and other key genes, such as AURKA, a cell cycle checkpoint mediator, and SPP1, LAMA3 and GJA1, which play a role in cell communication." (PMID 23383013, 2013). "However, recent studies of clinical samples suggested a different role of connexins in that expression levels and membrane localization of connexins, including Connexin 43 (Cx43, GJA1) and Connexin 26 (Cx26, GJB2), were found to be enhanced in metastatic lesions of cancer patients." (PMID 30642339, 2019). "Four genes (SERPINB7, INHBA, GJA1, and NID1) have two isoforms that have significantly different expression between the cancer and non-oncogenic groups." (PMID 23594586, 2013). "Interestingly, we observed an increase in GJA1 following CPT and paclitaxel treatment but not after carboplatin or ZA treatment, indicating the need for specific assessment of each connexin in personalized cancer treatment." (PMID 39594803, 2024).
infection (58 papers, 2006 to 2026). The state of being infected such as from the introduction of a foreign agent such as serum, vaccine, antigenic substance or organism. "The present study observed significantly lower expression of the gene that encodes Cx43 (Gja1) in mice at six months after infection, similarly to previous studies reporting the downregulation of Cx43 in the heart." (PMID 39136016, 2024). "Interestingly, we identified the GJA1 gene, which encodes Cx43, as one of the putative hits affected during the infection process, with a decrease in the expression levels over time." (PMID 37733471, 2023). "Nine down-regulated DEGs were commonly downregulated in response to either Aβ pathology or MA10 infection (Vegfa, Atp1a2, Slc6a11, Gja1, Slc6a11, Gpr37l1, Plpp3, Gstm1, Agt)." (PMID 41497643, 2025). "Gene profiling of T. cruzi-infected cardiomyocytes revealed suppression of GJA1 and GJC1 genes, which encode for Cx43 and Cx45 proteins, respectively, at 48 hours after infection." (PMID 24236292, 2013). "The expression of Gja1, which encodes Cx43, was reduced in the hearts of chagasic mice compared to naïve mice at 6 months, but not at 12 months after infection." (PMID 39136016, 2024). "An upregulated expression of the GJA1 gene has been demonstrated to play a significant role in the vesicle-mediated transport of the transcellular location of Borrelia bavariensis and resulting in infection of the human brain microvascular endothelial cells." (PMID 37374977, 2023). "Western blot assay revealed that the protein level of GJA1 was decreasing over the infection time." (PMID 27213338, 2016). "However, at 12 months after infection, higher Gja1 expression was noted, which may indicate the presence of a compensatory mechanism in response to the cardiac damage caused during disease progression." (PMID 39136016, 2024).
cardiac disease (41 papers, 2008 to 2025). "A substantial number of genetic variants in the genes DSP, JUP, DSC2, KLHL24 and GJA1 have been reported to underly skin and/or cardiac disease." (PMID 36142674, 2022). "As a consequence, it seems not to be reasonable to assume that a single point mutation in the Cx43 (GJA1) gene might be responsible for this cardiac malformation but rather a complex interaction of several factors that might cause inborn cardiac diseases." (PMID 24751918, 2014). "Ectopic expression of GJA1-20k has been found to rescue gap junction loss during acute ischemia, proving that modulating alternative translation initiation may protect against loss of electrical coupling, particularly in heart disease." (PMID 40869184, 2025). "In addition to GJA1 and GJA5, one mutation (p.Arg75His) in the GJC1 (encoding Cx45) gene has been reported to be related to heart disease to date." (PMID 35457072, 2022). "GJA1 and KCNJ2, both targeted by miR-1, are two ion channel genes, which are known to play a major role in cardiac disease and development." (PMID 31836860, 2019). "The non-canonical translation initiation of GJA1-20k exemplifies the role of alternative translation initiation related to cardiac disease." (PMID 40869184, 2025).
neurodegenerative disease (25 papers, 2015 to 2026). A disorder of the central nervous system characterized by gradual and progressive loss of neural tissue and neurologic function. "Many studies coupled GJA1 with the pathogenesis of neurodegenerative diseases such as AD, most notably finding GJA1 incorporated into amyloid plaques and upregulated in AD models and human brain." (PMID 33530349, 2021). "The network is constructed 13 drugs, a candidate genes GJA1 and neurodegenerative diseases." (PMID 35401145, 2022).
cardiovascular diseases (17 papers, 2015 to 2025). "Cardiovascular diseases influence alternative Cx43 translation; for instance, in a mouse model of arrhythmogenic cardiomyopathy, the amount of Gja1-20k is reduced." (PMID 40149906, 2025). "Numerous studies have documented the therapeutic efficacy of GJA1-20k gene therapy in animal models of cardiovascular disease." (PMID 39765713, 2024). "GJA1-20k represents a promising therapeutic target for the treatment of cardiovascular diseases." (PMID 39765713, 2024). "The clinical relevance of GJA1-20k is particularly evident in the context of cardiovascular diseases, where its roles in Cx43 trafficking, cytoskeleton remodeling, and mitochondrial homeostasis are critical for maintaining cardiac function and protecting the heart from injury." (PMID 39765713, 2024).
skin disorder (11 papers, 2011 to 2024). Any deviation from the normal structure or function of the skin or subcutaneous tissue that is manifested by a characteristic set of symptoms and signs. "GJA1 mutations have been shown to lead to various hereditary skin disorders." (PMID 38827992, 2024). "Up to now, at least 20 genes of human connexins are known, but skin disorders are only connected with mutations in GJB2 (Cx26), GJB6 (Cx30), GJB3 (Cx31), GJB4 (Cx30.3), and GJA1 (Cx43)." (PMID 25575739, 2015).
genetic disorders (8 papers, 2014 to 2023). "For example, mutations in the human GJA1 gene encoding Cx43 can cause a number of distinct rare genetic disorders." (PMID 36768546, 2023). "Mutations in one of these genes, GJA1 gene encoding Cx43, cause a number of rare genetic diseases, including skin disease." (PMID 30631135, 2019).
bacterial infection (7 papers, 2012 to 2022). "Several genes expressed higher in cPLA2α+/+ thancPLA2α-/- RPM are involved in host defense such as thegap junction protein, alpha 1 (Gja1, Vascular developmentcluster).GJA1 promotes phagocytosis and host survival to bacterial infection." (PMID 23950842, 2013). "In fact, the expression of GJA1, a member of the connexin gene family with a role in innate and adaptive immunity through the regulation of phagocytosis by macrophages and the host response to bacterial infection, was upregulated in infected pigs." (PMID 22935149, 2012).
brain diseases (4 papers, 2020 to 2025). "Although Gja1 plays an important role in brain homeostasis and brain diseases, its precise roles in specific cell types remain unclear." (PMID 36675286, 2023).
neurodevelopmental disorder (1 paper, 2024). A behavioral and cognitive disorder with onset during the developmental period that involves impaired or aberrant development of intellectual, motor, or social functions. "Recently, we identified a novel GJA1 variant in an undiagnosed patient with a neurodevelopmental disorder; however, the variant was identified as mosaic." (PMID 38221519, 2024).
peripheral nervous system disease (1 paper, 2023). "A number of these, including connexin 26 (Cx26)/GJB2, Cx29/Cx31.3/GJC3, Cx30/GJB6, Cx32/GJB1, Cx36/GJD2, Cx43/GJA1, Cx45/GJC1 and Cx47/GJC2 are expressed in the central and/or peripheral nervous system and mutations in a number of these cause central and/or peripheral nervous system disease." (PMID 37189458, 2023).
GJA1 also shares sentences with these, for which no sentence is quoted: cardiac arrhythmias (48 papers); epilepsy (41); Stroke (31); Myocardial fibrosis (25); ventricular tachycardia (22); diabetic retinopathy (21); ischemic stroke (18); Cognitive impairment (17); Duchenne muscular dystrophy (16); Parkinson disease (16); ischemic heart disease (14); kidney disease (14); osteoarthritis (14); bladder cancer (13); congestive heart failure (13); diabetic nephropathy (13); fibrosis (13); ventricular fibrillation (13); multiple sclerosis (12); myocarditis (12); chronic kidney disease (11); lung adenocarcinoma (11); malignant glioma (11); neuroblastoma (11); osteoporosis (11); inflammation (10); injury (10); lymph node metastasis (10); amyotrophic lateral sclerosis (9); neurological diseases (9).
A further 427 diseases each share a sentence with GJA1 in 8 papers or fewer.